FABP3 (fatty acid binding protein 3)
Diseases named in the same sentence as FABP3 in open-access papers (continued):
Sharing a sentence is not in itself a finding about the gene and the disease.
osteoporosis (4 papers, 2021 to 2025). A condition of reduced bone mass, with decreased cortical thickness and a decrease in the number and size of the trabeculae of cancellous bone (but normal chemical composition), resulting in increased fracture incidence. "In our study, we verified that MGP governs adipogenic differentiation by upregulating the transcription of FABP3 in MSCs and contributes to osteoporosis by affecting the Ca2+/CaMKII/RIP140 pathway." (PMID 40216750, 2025). "Cellular senescence also leads to a decrease in Optineurin (OPTN), an autophagy receptor therefore contributing to osteoporosis alongside with accumulation of the OPTN substrate fatty acid binding protein 3 (FABP3)." (PMID 34447754, 2021). "For instance, OPTN dysfunction regulates bone lipid homeostasis in the bone marrow cavity via the substrate fatty acid binding protein 3 (FABP3), leading to the onset of senile osteoporosis, and OPTN mutations maybe result in lipid metabolism abnormalities in patients and models of ALS." (PMID 38178841, 2023). "optn−/− mice show reduced ability to eliminate FABP3 (fatty acid binding protein 3, muscle and heart) by selective autophagy linked to impaired osteogenesis and increased bone loss, thus supporting the notion that decreased expression of OPTN during aging might lead to osteoporosis." (PMID 34459017, 2021). "In summary, our research has unveiled the regulatory role of MGP/Ca2+/CaMKII/RIP140/FABP3 axis in adipogenic differentiation in MSC and it might be a promising approach for osteoporosis treatment." (PMID 40216750, 2025).
sarcopenia (4 papers, 2020 to 2026). Progressive decline in muscle mass due to aging which results in decreased functional capacity of muscles. "Among them, FABP3 expression demonstrated better performance than the other parameters did in the sarcopenia diagnostic model." (PMID 41460756, 2026). "Collectively, we suggest that FABP3 would be a valuable therapeutic target for intervention of sarcopenia." (PMID 33168829, 2020). "In general, the categories with sarcopenia status (SPPB score ≤ 8 or SARC-F score ≥ 4) were associated with higher levels of P3NP, CAF22, osteonectin, FABP3 and MIF and lower levels of irisin in the individual cohorts of healthy controls, COPD and CHF patients." (PMID 33883602, 2021). "Therefore, FABP3 drives membrane lipid composition-mediated ER stress to regulate muscle homeostasis during aging and is a valuable target for sarcopenia." (PMID 33168829, 2020). "The FABP3 (P < 0.001), PECR (P < 0.01), and OPN3 (P < 0.001) mRNA expression markedly increased in sarcopenia versus control groups." (PMID 41460756, 2026). "Among various candidates investigated, circulating levels of P3NP, CAF22, osteonectin, irisin, FABP3 and MIF were significantly different in the COPF and CHF subjects with advanced sarcopenia, when compared to age-matched healthy controls." (PMID 33883602, 2021). "The qPCR results demonstrated that FABP3 (P < 0.001), PECR (P < 0.01), and OPN3 (P < 0.001) expression markedly increased in D‐gal‐induced sarcopenia compared with control groups, whereas PCTP (P < 0.001), SREBF2 (P < 0.001), and PPARGC1A (P < 0.05) levels dramatically decreased." (PMID 41460756, 2026). "FABP3, PPARGC1A, and SREBF2 received the highest relevance scores, indicating that these genes may serve as more prominent mediators linking sarcopenia with fatty acid metabolism." (PMID 41460756, 2026).
schizophrenia (4 papers, 2014 to 2023). A major psychotic disorder characterized by abnormalities in the perception or expression of reality. "This study aimed to explore the association of circulating FABP3/FABP4 levels with HRV in patients with chronic schizophrenia." (PMID 37255976, 2023). "In keeping with this conclusion, a FABP3 frameshift mutation, which could potentially result in a loss of gene function, was found in a patient with residual schizophrenia." (PMID 25027319, 2014). "Brains with AD and schizophrenia were found to have reduced Fabp3 levels, and serum Fabp3 levels are elevated in multiple dementia and brain injury syndromes." (PMID 30253800, 2018). "In another study, resequencing analysis of FABP3, FABP5 and FABP7 from an ASD cohort identified several rare non-synonymous polymorphisms, some of which were also seen in schizophrenia." (PMID 25027319, 2014). "In this study, we performed comprehensive analyses of FABP7, FABP5 and FABP3, in the context of psychiatric illnesses, particularly schizophrenia and ASD." (PMID 25027319, 2014). "A previous study demonstrated that changes in the level of FABP3 in the brain may represent a disease mechanism in some patients with schizophrenia and autism spectrum disorder." (PMID 37255976, 2023). "Increased FABP3 and FABP4 levels may be associated with CVD-related health problems in patients with chronic schizophrenia." (PMID 37255976, 2023). "Dysfunction of FABP3 protein binding to D2L-R was shown in FABP3 KO mice, which affects emotional behavior, and is characteristic of neurodegenerative diseases such as schizophrenia and Alzheimer’s disorder." (PMID 32977535, 2020). "Furthermore, we identified and reported several rare non-synonymous polymorphisms of the brain-expressed genes FABP3, FABP5 and FABP7 from schizophrenia and autism spectrum disorder (ASD), diseases known to part share genetic architecture." (PMID 25027319, 2014). "In addition, FABP3, 5 and 7 genes are not included in the copy number variation loci that have been reported to be associated with schizophrenia and ASD." (PMID 25027319, 2014).
subarachnoid hemorrhage (4 papers, 2017 to 2023). A serious neurological disorder characterized by intracranial hemorrhage into the subarachnoid space. "For instance, both elevated MIF and FABP3 have been previously shown to be linked to worse clinical outcome after subarachnoid hemorrhage and brain injury." (PMID 37277809, 2023). "This is confirmed by the parallel increase in FABP3 and tau in other conditions, such as CJD, subarachnoid hemorrhage, and VAD." (PMID 28750675, 2017).
amyloid (3 papers, 2017 to 2025). "The association with amyloid pathology was also found in our study, where CSF levels of FABP3 and tau proteins were increased in Aβ1–42-positive subjects, similarly to a recent report." (PMID 28750675, 2017). "However, previous research has demonstrated significantly elevated GOT activity in the brains of Alzheimer’s patients.Elevated levels of FABP3 have been demonstrated to be associated with an increased likelihood of amyloid pathology." (PMID 40033432, 2025). "Furthermore, according to previously published data, protein levels of FABP3 and CAPG may increase in an age-dependent manner in microglia of amyloid mouse models, while the protein levels of MDH1 appear to decrease in the very same mice." (PMID 37775827, 2023).
aortic valve disease (3 papers, 2016 to 2022). "For example, FABP3 and EHHADH were up-regulated in the left atria of mitral regurgitation patients compared to in patients with aortic valve disease and normal controls." (PMID 35055737, 2022). "Notably, only ACADM, FABP3, ECH1, ACAA2, EHHADH, CPT1A and PLTP of the PPAR pathway were significantly differentially expressed in the MR patients compared to patients with aortic valve disease and normal controls." (PMID 27250500, 2016). "Notably, only ACADM, FABP3, ECH1, ACAA2, EHHADH, CPT1A and PLTP of the PPAR signaling pathway were differentially expressed in the left atria of MR patients compared to patients with aortic valve disease and normal controls." (PMID 27250500, 2016). "Notably, seven genes (ACADM, FABP3, ECH1, ACAA2, EHHADH, CPT1A and PLTP) of the PPAR signaling pathway were differentially expressed in the left atria of MR patients compared to patients with aortic valve disease and normal controls." (PMID 27250500, 2016).
atrial fibrillation (3 papers, 2019 to 2020). A disorder characterized by an electrocardiographic finding of a supraventricular arrhythmia characterized by the replacement of consistent P waves by rapid oscillations or fibrillatory waves that vary in size, shape and timing and are accompanied by an irregular ventricular response. "In humans, FABP3 gene expression in the atrium was reduced in patients with post-operative atrial fibrillation." (PMID 30892277, 2019).
Cachexia (3 papers, 2021 to 2024). Severe weight loss, wasting of muscle, loss of appetite, and general debility related to a chronic disease. "Patients with cachexia had significantly higher levels of fatty acid-binding protein 3 (FABP3), follistatin-like 1 protein (FSTL−1), interleukin 6 (IL 6), and interleukin 8 (IL 8), while leptin concentrations in the peripheral blood were significantly lower." (PMID 39411315, 2024). "Interestingly, many of the cachexia associated genes such as FOXO1, FOXO3, SIRT1, SMAD3 and FABP3 were identified in age related gene expression in similar direction." (PMID 33923976, 2021). "No further clinical data could be identified linking FABP3 or follistatin-like protein 1 (FSTL−1) with cachexia." (PMID 39411315, 2024). "In cancer-induced cachexia, the levels of several myokines—including myostatin, IL-15, follistatin-related protein 1 (FSTL-1), fatty acid binding protein 3 (FABP3) and irisin—are elevated, suggesting that inhibition of myokines could be a therapeutical approach." (PMID 34899373, 2021).
COVID-19 (3 papers, 2020 to 2023). A disease caused by infection with severe acute respiratory syndrome coronavirus 2. "Our data demonstrated that serum biomarkers HMGB1, myoglobin, FABP3 and troponin I were significantly altered during the initial phase of COVID-19." (PMID 37662953, 2023).
dementia with Lewy bodies (3 papers, 2021 to 2023). "In Lewy body diseases, the pathogenic protein α-synuclein propagates and FABP3 participates in this process." (PMID 37686075, 2023). "This suggests the potential of FABP3 as a general biomarker of Lewy body disease." (PMID 37686075, 2023). "The intricate involvement of FABPs, particularly FABP3, FABP5, and FABP7, in the pathogenesis of Lewy body diseases highlights their significance in reflecting the disease state." (PMID 37686075, 2023).
dilated cardiomyopathy (3 papers, 2011 to 2021). Cardiomyopathy which is characterized by dilation and contractile dysfunction of the left and right ventricles. "Next, we assessed the transcriptional expression of Fabp3 in the single-cell RNA-sequencing (scRNA-seq) datasets, which analyzed the transcriptional profile of murine cardiomyocytes after TAC surgery, and the scRNA-seq from dilated cardiomyopathy (DCM) or normal patients." (PMID 34458345, 2021).
Down syndrome (3 papers, 2016 to 2021). "FABP7 is overexpressed in Down syndrome adult and fetal brains, whereas FABP3 is significantly decreased in Down syndrome adult brains." (PMID 34208549, 2021).
non-alcoholic fatty liver disease (3 papers, 2015 to 2023). "Dysregulation was established for FABP3 in cardiovascular disorders, FABP1, FABP2, FABP4 and FABP5 in non-alcoholic fatty liver disease and FABP5 and FABP7 in cancer." (PMID 30386187, 2018).
ovarian carcinoma (3 papers, 2016 to 2025). A malignant neoplasm originating from the surface ovarian epithelium. "The network based approach identified two 7-gene functional interaction modules (31: DCLRE1A, EXO1, KIAA0101, KIN, PCNA, POLD3, POLD2; 35: DKK3, FABP3, IRF1, AIM2, GBP1, GBP2, IRF2) that are associated with prognosis of ovarian cancer patients." (PMID 27806724, 2016).
renal cell carcinoma (3 papers, 2011 to 2018). "FABP3, the most abundant protein we found in metastatic tumors, has been implicated in renal cell carcinoma, esophageal adenocarcinoma and as a mammary-derived growth inhibitor." (PMID 26305875, 2015).
vascular dementia (3 papers, 2020 to 2023). A degenerative vascular disorder affecting the brain. "FABP3 has been proposed as a potential biomarker of neurodegeneration, as increased levels of FABP3 have been observed in the cerebrospinal fluid (CSF) of patients with AD, PD, and vascular dementia." (PMID 32752296, 2020).
chronic obstructive pulmonary disease (2 papers, 2025). A chronic and progressive lung disorder characterized by the loss of elasticity of the bronchial tree and the air sacs, destruction of the air sacs wall, thickening of the bronchial wall, and mucous accumulation in the bronchial tree. "According to the DrugBank database, multiple drugs targeting IL-13 and IL-33, or carried by FABP3 to the heart, have been developed and either approved or are under investigation for conditions such as atopic dermatitis, asthma, chronic obstructive pulmonary disease and bacterial growth." (PMID 41391830, 2025).
colon adenocarcinoma (2 papers, 2025). "In colon adenocarcinoma (COAD) FABP3 is downregulated and has been identified as an independent prognostic factor in a PPAR-related gene signature." (PMID 41149452, 2025). "FABP3 has been identified as an independent prognostic factor for poor outcomes in patients with colon adenocarcinoma (COAD)." (PMID 40717587, 2025).
esophageal cancer (2 papers, 2023 to 2025). A primary or metastatic malignant neoplasm involving the esophagus. "FABP3 has been included in a multi-gene scoring model for predicting the prognosis of esophageal cancer patients." (PMID 40717587, 2025).
idiopathic dilated cardiomyopathy (2 papers, 2013 to 2021). Decreased function of the heart associated with cardiac enlargement and congestive heart failure, of unknown cause. "Previously, we found that FABP3 is highly expressed in patients with ventricular-septal defects and is often used as a plasma biomarker in idiopathic dilated cardiomyopathy, and may play a significant role in the development of these defects in humans." (PMID 23823803, 2013).
nicotine addiction (2 papers, 2021 to 2023). "This constitutively increased signaling could not trigger nicotine addiction and possibly become the underlying mechanism of the failure of nicotine-induced addiction in FABP3−/− mice." (PMID 33804804, 2021). "Future studies are required to demonstrate how MF1 affects the internalization of D2Rs through FABP3 and CaMKII/ERK signaling in models of nicotine addiction." (PMID 37047614, 2023).
pancreatic cancer (2 papers, 2018). "Knockdown of expression of either GDF15 or FABP3 using specific siRNA in AsPC-1 cells reversed the growth inhibitory effects of frondoside A. These findings suggest that both GDF15 and FABP3 are involved in the growth inhibitory effects of frondoside A in pancreatic cancer." (PMID 29463049, 2018).
psoriasis (2 papers, 2017 to 2019). An autoimmune condition characterized by red, well-delineated plaques with silvery scales that are usually on the extensor surfaces and scalp. "FABP4 may be a marker of psoriasis, and FABP3 may be associated with inflammation or liver disorders in psoriatic patients." (PMID 27864793, 2017). "A positive correlation between FABP3 and white blood count or liver enzyme activity points to a possible indication of inflammation or a link between psoriasis and liver disorders." (PMID 27864793, 2017). "Nevertheless, it underscores the uniqueness of the present study and the need for further study to determine the precise role of FABP4 and FABP3 in the pathogenesis of psoriasis and its comorbidities." (PMID 27864793, 2017). "We did not confirm the possible involvement of FABP3 in the risk assessment of CMDs in patients with psoriasis, but we have indicated possible link with chronic inflammation and liver dysfunction." (PMID 30993401, 2019). "A second objective of the study was to assess whether FABP3 and FABP4 could be useful for predicting the risk of cardiovascular disorders or metabolic diseases in patients with psoriasis." (PMID 27864793, 2017). "In summary, FABP4 and FABP3 may play a pivotal role in numerous disorders, including obesity, atherosclerosis, MS, IR and CAD, which are closely associated with psoriasis." (PMID 27864793, 2017). "A statistically significant association between FABP3 and AST activity points to some unknown link with liver function or perhaps non-alcoholic fatty liver disease (NAFLD) and psoriasis." (PMID 27864793, 2017). "However, the concentration was almost 2.5 times as high in persons with PASI 10–20 as in controls, indicating that FABP3 could have some relevance in patients with moderate psoriasis." (PMID 27864793, 2017). "From the remaining FABPs only heart—(H-FABP, FABP3) and adipocyte fatty acid-binding protein (A-FABP, FABP4) were evaluated in patients with psoriasis in the research conducted by us." (PMID 30993401, 2019). "The lowest FABP3, 6.8 (2.1–30.0) ng/ml and slightly lower than that of the controls, was noted in the group with severe psoriasis (p = 0.96), but it was not statistically significant." (PMID 27864793, 2017).
adenoma (1 paper, 2025). A neoplasm arising from the epithelium. "Not only for the differentiation of BTN and TC, we also found interesting variation of FABP3 methylation in variant subtypes of BTN (adenoma, goiter, subacute thyroiditis, lymphatic thyroiditis) and TC (PTC, FTC, MTC, ATC)." (PMID 41019337, 2025). "As for BTN, the methylation level of FABP3 in patients with lymphatic thyroiditis was lower than that in patients with adenoma (all the P values ≤ 0.002)." (PMID 41019337, 2025). "Adenoma showed the highest FABP3 methylation among all the BTN and TC subgroups, followed by goiter and subacute thyroiditis." (PMID 41019337, 2025). "Our study showed similar FABP3 methylation level in FTC with adenoma, indicating that follicular adenoma may share common epigenetic background with FTC as well." (PMID 41019337, 2025). "All seven FABP3 CpG sites were hypomethylated in PTC, MTC, and ATC cases than those in adenoma patients (all the P values ≤ 5.90E - 05)." (PMID 41019337, 2025). "FABP3 methylation was varied in BTN and TC subtypes, with the highest level in adenoma and the lowest in anaplastic thyroid cancer." (PMID 41019337, 2025). "However, we did not observe a difference in FABP3 methylation between adenoma subjects and FTC cases (all the P values > 0.05)." (PMID 41019337, 2025).
brain infarction (1 paper, 2021). Tissue necrosis in any area of the brain, including the cerebral hemispheres, the cerebellum, and the brain stem. "In this study, we demonstrated that MF6 decreased brain infarction volumes and neurological deficits in mice subjected to tMCAO and reperfusion by inhibiting FABP3, FABP5 and FABP7 expression in the brain." (PMID 34068550, 2021).
Brugada syndrome (1 paper, 2021). A genetically heterogeneous condition characterized by complete or incomplete right bundle branch block accompanied by ST elevation in leads V1-V3. "Furthermore, FABP3 has been reported to be elevated in patients with Brugada syndrome and ventricular fibrillation despite the absence of structural heart disease and cardiac dysfunction." (PMID 33850478, 2021).
cortical dysplasia (1 paper, 2017). "And FSCN1, CRMP1, NDRG1, DPYSL5, MAP4, and FABP3 were selected for validation and identified to be increased in childhood cortical dysplasia patients, while PRDX6 and PSAP were identified decreased." (PMID 28222113, 2017). "In our study, a increased FABP3 level was found in CCD patients, possibly indicating early maturity of metabolism pattern in CCD patients, which may contribute to the formation of cortical dysplasia." (PMID 28222113, 2017).
experimental autoimmune encephalomyelitis (1 paper, 2017). An autoimmune demyelinating disease of the central nervous system that is produced experimentally in animals by the injection of homogenized brain or spinal cord in Freund's adjuvant. "Moreover, FABP3 deficiency in mice showed protective effect against experimental autoimmune encephalomyelitis, indicating a possible role of autoimmune inflammation in CCD." (PMID 28222113, 2017).